TRA2B (transformer 2 beta homolog)
Description:
Sequence-specific RNA-binding protein which participates in the control of pre-mRNA splicing. Can either activate or suppress exon inclusion. Acts additively with RBMX to promote exon 7 inclusion of the survival motor neuron SMN2. Activates the splicing of MAPT/Tau exon 10. Alters pre-mRNA splicing patterns by antagonizing the effects of splicing regulators, like RBMX. Binds to the AG-rich SE2 domain in the SMN exon 7 RNA. Binds to pre-mRNA.
Synonyms: TRA2-beta; hTRA2-beta; SFRS10; PPP1R156; RAMELN; SRFS10; TRAN2B
Tractability: PROTAC: UniProt records ubiquitination sites on it; ubiquitination databases record sites on it; its protein half-life has been measured.
Gene: Protein-coding gene on chromosome 3 (185,914,558 to 185,938,103, reverse strand). Ensembl gene ENSG00000136527.
Subcellular location: Nucleus
Subcellular location (Human Protein Atlas): Nucleoplasm
Pathways (Reactome):
Metabolism of RNA: Processing of Capped Intron-Containing Pre-mRNA; mRNA Polyadenylation; mRNA Splicing - Major Pathway
Signal Transduction: RHOBTB1 GTPase cycle; RHOBTB2 GTPase cycle
Gene Ontology:
Molecular function: identical protein binding; mRNA binding; pre-mRNA binding; protein binding; protein domain specific binding; RNA binding; nucleic acid binding
Biological process: cellular response to glucose stimulus; mRNA splicing, via spliceosome; positive regulation of mRNA splicing, via spliceosome; regulation of alternative mRNA splicing, via spliceosome; regulation of RNA splicing; RNA splicing, via transesterification reactions
Cellular component: nucleoplasm; nucleus; protein-containing complex; spliceosomal complex
Genetic constraint (gnomAD): Loss-of-function variants: 10 observed, 32.13 expected, observed/expected ratio (o/e) 0.31, 90% interval 0.19 to 0.53. The upper end of that interval is the gene's LOEUF score, 0.53, which puts it in group 2 of 6, group 1 being the genes least tolerant of losing a copy. Missense variants: 140 observed, 358.5 expected, observed/expected ratio (o/e) 0.39, 90% interval 0.34 to 0.45. Synonymous variants: 112 observed, 120.38 expected, observed/expected ratio (o/e) 0.93, 90% interval 0.8 to 1.09.
Gene-disease validity (ClinGen):
ClinGen rates the evidence that TRA2B causes each of these diseases.
syndromic complex neurodevelopmental disorder (autosomal dominant): Definitive. A disorder that involves more than one phenotype associated with the central nervous system, including but not limited to intellectual disability, autism, and seizures (epilepsy), and also a distinctive pattern of other features including dysmorphisms and/or congenital malformations.
Homologues: Orthologues: chimpanzee TRA2B (100% identical), dog TRA2B (100% identical), macaque TRA2B (100% identical), mouse Tra2b (100% identical), pig TRA2B (100% identical), rabbit TRA2B (100% identical), guinea pig TRA2B (93% identical), tropical clawed frog tra2b (92% identical), rat Tra2b (91% identical), zebrafish tra2b (75% identical). Paralogues in human: TRA2A (69% identical).
Diseases named in the same sentence as TRA2B in open-access papers:
TRA2B is named in the same sentence as 66 diseases in open-access papers, as found by Europe PMC text mining. Sharing a sentence is not in itself a finding about the gene and the disease. The quoted sentences say what the papers report.
breast carcinoma (11 papers, 2008 to 2025). "In MDA-MB-231 breast cancer cells, TRA2β binds to a poison exon in the TRA2α transcript, meaning that TRA2 upregulation can suppress TRA2α expression." (PMID 41009380, 2025). "The implication of splicing factors SRSF4, SRSF6 and TRA2β was already demonstrated in cell proliferation and invasion promotion in normal mammary cells and in breast cancer cells." (PMID 37904233, 2023). "For example, both SRSF3 and TRA2β are frequently upregulated in breast cancer and regulate the splicing of CD44 leading to the expression of the CD44v isoform that is associated with increased stemness and metastatic traits." (PMID 36980782, 2023). "The expression of the RBPs TRA2α/TRA2β correlated with invasiveness in breast cancers and a poor prognosis in cervical cancer." (PMID 36980782, 2023). "In the breast cancer tissue group, TRA2B, RHOA, and THRAP3 were the most stable genes, and DNAJC8, GAPDH, and B2M were the most unstable genes." (PMID 34895237, 2021). "On the other hand, NormFinder and the ΔCt method recommended TRA2B as most appropriate for normalizing expression in breast cancer tissue samples." (PMID 34895237, 2021). "Remarkably, Tra2β has recently been found altered in approximately 13% of breast cancer specimens, 0.5–1.5% of hematological malignancies, and in lung cancers." (PMID 33143085, 2020). "The high expression of TRA2B is closely related to the cancer cell survival and therapeutic sensitivity of breast cancer." (PMID 32461838, 2020). "Among these targets, SRSF1 and TRA2B are key splicing activators, both involved in dysregulated splicing in breast cancer." (PMID 30658617, 2019). "TRA2β expression may also be controlled by estrogen, in which estrogen is a receptor for positive breast cancer cell development." (PMID 41009380, 2025). "Therefore, we considered the multi-RG combination SF1 + TRA2B + THRAP3 + RHOA + QRICH1 as the most promising choice for breast cancer research (both in breast cancer tissues and cell lines)." (PMID 34895237, 2021). "Furthermore, SR splice factor TRA2β is overexpressed in invasive breast cancer and induces exon v4 and v5 inclusion, suggesting that besides the standard CD44 isoform also the v4 and v5 isoforms are related to increased invasion and metastasis formation." (PMID 31666932, 2019). "Interestingly, splice factors TRA2α and TRA2β are clearly upregulated in breast cancer and those oncogene-like factors limit the amount of DNA damage thereby preventing cell death before entering the G2 phase." (PMID 31666932, 2019). "TRA2B showed the lowest prediction error over all subtypes and had previously been shown to be specifically induced in breast cancer, and more induced in invasive breast cancers compared to non-invasive breast cancers, perhaps by splicing CD44 isoforms." (PMID 28589855, 2017). "There was also a moderate-to-high correlation (R2 from 0.621 to 0.709 in breast cancer tissues, and R2 from 0.600 to 0.916 in breast cancer cell lines) between unstable RGs and SF1 + TRA2B + THRAP3 + RHOA + QRICH1." (PMID 34895237, 2021). "The top three genes for breast cancer tissues and cell lines were SF1 + TRA2B + THRAP3 and THRAP3 + RHOA + QRICH1, respectively, and therefore a total of 5 RGs (SF1, TRA2B, THRAP3, RHOA, QRICH1) should be considered." (PMID 34895237, 2021). "There was a high correlation (R2 from 0.815 to 0.979 in breast cancer tissues, and R2 from 0.927 to 0.995 in breast cancer cell lines) between stable RGs and SF1 + TRA2B + THRAP3 + RHOA + QRICH1." (PMID 34895237, 2021). "Our results show that RG combinations SF1 + TRA2B + THRAP3 and THRAP3 + RHOA + QRICH1 showed stable expression in breast cancer tissues and cell lines, respectively, and that they displayed good interchangeability." (PMID 34895237, 2021).
breast carcinoma (continued). "According to the ΔCt method, TRA2B, RHOA, and THRAP3 were the most stably expressed genes, while DNAJC8, GAPDH, and B2M were the least stable genes in the breast cancer tissue group, which was consistent with the analysis according to NormFinder." (PMID 34895237, 2021). "Our results indicated that SF1, TRA2B, and THRAP3 were the top 3 stably expressed RGs in breast cancer tissues and that THRAP3, RHOA, and QRICH1 were the top 3 stably expressed RGs in breast cancer cell lines." (PMID 34895237, 2021). "In breast cancer cell lines, when the optimal RG combinations SF1 + TRA2B + THRAP3 + RHOA + QRICH1, SF1 + TRA2B + THRAP3, or THRAP3 + RHOA + QRICH1 were used for normalization, the expression of FAAH was highest in MCF-7 cells, followed by MCF-10A cells, and was least in MDA-MB-231 cells." (PMID 34895237, 2021). "Therefore, we recommend that SF1 + TRA2B + THRAP3 and THRAP3 + RHOA + QRICH1 be adopted as the RG combinations for breast cancer tissue and cell line research, respectively." (PMID 34895237, 2021). "Therefore, to confirm the roles of these genes on the vital regulatory mechanisms in breast cancer, we compared the potential role of novel RGs (SF1, TRA2B, THRAP3, RHOA, and QRICH1) vs. traditional RGs (ACTB, and GAPDH) in the normalization of target gene expression." (PMID 34895237, 2021).
colon cancer (8 papers, 2013 to 2021). "TRA2B exon 2 has premature stop codons, whereas an exon 2-containing splice variant (TRA2β4) was expressed preferentially in the nuclei of human colon cancer cells." (PMID 27043659, 2016). "Both TRA2B RNA and Tra2β protein levels are upregulated in breast, cervical, ovarian, and colon cancer, and Tra2β expression is associated with cancer cell survival." (PMID 23935626, 2013). "Thus, ectopic overexpression of Tra2β protein and TRA2β4 RNA causes abnormal growth of colon cancer cells." (PMID 31311954, 2019). "Tra2β protein and TRA2β4 play crucial roles in abnormal colon cancer cell growth, and G4 is now recognized as a crucial regulator for cancer-related genes." (PMID 31311954, 2019). "Based on these findings, both Tra2β and TRA2β4 are considered to be new targets for treatment of colon cancer." (PMID 31311954, 2019). "Given that TRA2β mRNA expression is significantly upregulated in colon cancer and prostate cancer tissues compared with paired normal tissues, it is highly possible that TRA2β plays an important role in carcinogenesis by blocking function of miR-204." (PMID 27438705, 2016). "Knockdown of Tra2β in colon cancer cells reduced cell viability and increased the level of apoptosis monitored using a TUNEL assay and through measurement of levels of cleaved PARP." (PMID 23935626, 2013). "Interestingly, knockdown of HNRNPA1 was reported to positively regulate transcription of TRA2B in colon cancer cells." (PMID 32631453, 2020). "Our results suggest that hnRNPA1 may modulate TRA2B transcription through its regulation of G4 formation in its promoter in colon cancer cells." (PMID 31311954, 2019). "However, further experiments are needed to characterize structure and dynamics of G4 in the TRA2B promoter in colon cancer cells." (PMID 31311954, 2019). "Although this is the limited survey, these results suggest that hnRNPA1 and hnRNPU may contribute Tra2β overexpression in colon cancer cells." (PMID 31311954, 2019). "Overexpressed Tra2β could increase Bcl-2 expression through competition with miR-204, facilitating colon cancer cell growth." (PMID 31311954, 2019). "The present study suggests that the TRA2B gene may control both apoptosis and senescence of colon cancer cells by generating different splice isoforms (TRA2β1 and TRA2β4)." (PMID 27043659, 2016). "TRA2B4 is upregulated in colon cancer cell lines, although it is not translated to Tra2β protein because of its nuclear retention." (PMID 33883665, 2021). "Tra2β protein interacts with the BCL2 3′-UTR and promotes abnormal growth of colon cancer cells." (PMID 31311954, 2019).
Obesity (6 papers, 2012 to 2025). Accumulation of substantial excess body fat. "This pattern has also been observed in mouse models of diet‐induced obesity, where downregulation of the trans‐acting factor TRA2B led to increased lipogenesis through the altered splicing and expression of the lipogenic β isoform of LPIN1." (PMID 40425033, 2025). "Regulation of Tra2β may also be related to energy status as individuals with obesity have lower skeletal muscle and adipose expression of Tra2β compared to lean individuals." (PMID 30781793, 2019).
cervical carcinoma (5 papers, 2013 to 2020). A carcinoma arising from either the exocervical squamous epithelium or the endocervical glandular epithelium. "Tra2β upregulation is associated with invasive breast cancer, and medium to high Tra2β expression correlates with a poorer prognosis in cervical cancer compared to patients with lower expression levels." (PMID 23935626, 2013). "Upregulation of Tra2β protein has been associated with aggressiveness in cervical cancer; however the role of this protein in lung cancer is unknown." (PMID 26444668, 2015). "Specifically, the over expression of Tra2β protein, which localizes to the cervical carcinoma cell nuclei, was demonstrated to correlate with lymph node metastasis, higher tumor grade, size and depth of invasion." (PMID 32596243, 2020). "Other proteins involved in splicing processes, including Tra2β, Brm and Sam68, have been found deregulated in cervical cancer and derived cell lines and proposed to have significant roles in cervical carcinogenesis." (PMID 32596243, 2020). "Tra2b gained increasing significance in cancer research as its expression has shown to be elevated in lung, ovarian and cervical carcinomas." (PMID 24586484, 2014). "TRA2B over-expression was observed in endometrial cancers, Gastric cancer cells and cervical cancer." (PMID 23874428, 2013).
lung carcinoma (5 papers, 2015 to 2022). "Overexpression of several SR and SR-like proteins, in particular SRSF1, SRSF3, SRSF6 and TRA2β, was observed in lung cancer." (PMID 34065983, 2021). "Previous studies found a role for TRA2B in embryonic tissue development and identified TRA2B as a survival factor for neoplasia such as prostate cancer, glioma, and lung cancer." (PMID 32631453, 2020). "TRA2B amplification has been described in several neoplasms, including lung cancer." (PMID 26444668, 2015). "Since SMN protein as part of the SMN complex is essential to chaperone the assembly of the Sm-snRNA complexes that form the cores of the spliceosome subunits, we hypothesize that TRA2β overexpression in lung cancer cells might perhaps promote efficient mRNA splicing." (PMID 34065983, 2021).
osteosarcoma (5 papers, 2021 to 2024). A usually aggressive malignant bone-forming mesenchymal neoplasm, predominantly affecting adolescents and young adults. "It has been reported that transformer 2 beta homolog (TRA2B) is overexpressed during the progression of osteosarcoma, and BMMSCs-Exo can carry miR-206 and target TRA2B to inhibit the progression of this disease." (PMID 38994350, 2024). "Such as, Zhang and colleagues reported that BMSC-derived exosomes inhibited the proliferation, migration, and invasion of osteosarcoma cells and induced their apoptosis both in vitro and in vivo by delivering miR-206 and inhibiting TRA2B expression." (PMID 37377390, 2023). "The exosomal miR-206 derived from bone marrow mesenchymal stem cells inhibits osteosarcoma progression by targeting TRA2B." (PMID 36545680, 2022). "Moreover, BMSC-derived exosomes inhibited osteosarcoma progression by transferring miR-206 and inhibiting transformer 2 protein homolog beta (TRA2B)." (PMID 37377390, 2023). "Since TRA2B is associated with EMT-related proteins (twist, N-cadherin, and E-cadherin), miR-206 encapsulated in exosomes could also impede the osteosarcoma metastasis by downregulating TRA2B-induced EMT." (PMID 35592419, 2022).
prostate carcinoma (5 papers, 2016 to 2026). A carcinoma that arises from epithelial cells of the prostate gland. "The splicing regulator protein Tra2β also increases the expression in prostate cancer tissues, and this is associated with preoperative prostate-specific antigen, lymph node metastasis, clinical stage, Gleason score and biochemical recurrence." (PMID 28382513, 2017). "Additionally, the splicing regulator TRA2B has been linked to alternative splicing that drives cancer pathways and metastasis in various cancer types, including prostate cancer." (PMID 40491606, 2025). "The splicing regulators Sam68 and Tra2β increase expression in prostate cancer." (PMID 28382513, 2017). "Interestingly, joint depletion of Tra2β and its ortholog Tra2α inhibits CHK1 exon 3 splicing in the LNCaP prostate cancer cell line." (PMID 28382513, 2017).
spinal muscular atrophy (4 papers, 2014 to 2025). A motor neuron disease that affect the muscles, and characterized by muscle weakness and atrophy resulting from progressive degeneration and irreversible loss of the anterior horn cells in the spinal cord (i.e., lower motor neurons) and the brain stem nuclei. "Specific TRA2B-related splicing processes have been implicated in human diseases like spinal muscular atrophy (splicing of SMN) and in tauopathies like Alzheimer’s disease and FTDP-17 (splicing of MAPT)." (PMID 24586484, 2014). "VPA, used for conditions like bipolar disorder, migraine, epilepsy, and spinal muscular atrophy with anti-cancer side effects, also promotes splicing inclusion of SM2 exon 7 via TRA2β mediated mechanism." (PMID 41009380, 2025).
breast tumor (3 papers, 2013 to 2021). "Approximately 13% of recurrent mutations of Tra2β have been found in TCGA human breast tumors sorted by frequency." (PMID 33143085, 2020). "Tra2β upregulation is enriched in basal breast tumors and an aggressive cancer subtypes." (PMID 33143085, 2020). "In particular, two CD44 internal variable exons, CD44v4 and CD44v5, increase their splicing inclusion in transfected HeLa cells in response to increased Tra2β protein expression, suggesting that Tra2β might also increase their inclusion in breast tumours with elevated Tra2β expression." (PMID 23935626, 2013). "In the breast tumor tissue group, the 3 most stably expressed RGs were SF1, TRA2B, and THRAP3." (PMID 34895237, 2021).
gastric cancer (3 papers, 2013 to 2022). A primary or metastatic malignant neoplasm involving the stomach. "Downregulation of Tra2β inhibits cell growth of a gastric cancer cell line, measured by a corresponding decrease in BrdU incorporation which monitors cells which have entered S phase." (PMID 23935626, 2013). "Tra2β translocates into the cytoplasm in gastric cancer cells in response to cell stress induced by sodium arsenate, and changes in the nuclear concentration of Tra2β might have downstream effects on the splicing inclusion of target exons." (PMID 23935626, 2013).
invasive breast carcinoma (3 papers, 2013 to 2024). A carcinoma that infiltrates the breast parenchyma. "TRA2B upregulation is associated with invasive breast cancer, and medium to high TRA2B expression correlates with a poorer prognosis." (PMID 38448406, 2024).
ovarian carcinoma (3 papers, 2020 to 2025). A malignant neoplasm originating from the surface ovarian epithelium. "While its oncogenic role has been reviewed previously, recent research continues to explore TRA2β’s specific therapeutic potential in ovarian cancer, squamous cell carcinoma, and colon adenocarcinoma." (PMID 41009380, 2025). "TRA2β upregulation was directly correlated with increased malignancy of ovarian cancer, reinforcing its role as a proto-oncogene in this disease." (PMID 41009380, 2025). "TRA2β has been shown to promote the progression of ovarian cancer in humans." (PMID 41009380, 2025). "Interestingly, proteins such as CCNE1, FASN, HDGF, MCM7, PIGR, PTK2, or TRA2B have been described as having a prognostic relation with some other type of gynecological cancer (breast, cervical or ovarian cancer)." (PMID 34680205, 2021).
Alzheimer disease (2 papers, 2013 to 2014). A progressive, neurodegenerative disease characterized by loss of function and death of nerve cells in several areas of the brain leading to loss of cognitive function such as memory and language. "In mammalian brain, a change of Tra2β concentration is concomitant with hypoxia, nerve injury and Alzheimer’s disease." (PMID 23977258, 2013).